G6PD (glucose-6-phosphate dehydrogenase)
Diseases named in the same sentence as G6PD in open-access papers (continued):
Sharing a sentence is not in itself a finding about the gene and the disease.
malaria (continued). "This hemolytic toxicity has raised significant concern because of the widespread prevalence of G6PD deficiencies in malaria endemic regions." (PMID 27053284, 2016). "A previous study reported that mutation in the G6PD gene gives boys substantial protection against severe malaria." (PMID 27109515, 2016). "Another possible option would be to introduce point-of-care rapid detection devices for glucose-6-phosphate dehydrogenase (G6PD) enzyme deficiency in malaria-infected patients." (PMID 27527707, 2016). "The risk of primaquine-induced hemolysis in G6PD deficient individuals is a significant public health concern in malaria endemic countries and a major barrier for better vivax malaria control." (PMID 26849445, 2016). "It is noteworthy that different prevalence and distribution patterns of G6PD variants have been reported from different malaria-endemic areas in the world." (PMID 27329471, 2016). "It is also postulated that G6PD deficiencies have become more frequent because G6PD-deficient variants confer some protection or resistance against malaria caused by the species P. falciparum and P. vivax." (PMID 27109515, 2016). "Further investigations are required in a larger population with well certain ethnic groups for a real estimate of the prevalence of Glucose-6-phosphate dehydrogenase variants involved in a possible association with the resistance to various kinds of malaria." (PMID 27413522, 2016). "G6PD deficient individuals, many of whom live in malaria endemic regions, are at risk of developing haemolytic crises triggered by several risk factors including multiple drugs and specific foods." (PMID 27225440, 2016). "Based on G6PD 202G>A and 376A>G SNPs only three malaria patients showed Gd A- deficiency and four women were 202A and 376G carriers." (PMID 27767381, 2016). "G6PDd based on enzymatic activity as well as G6PD A allelic variants were found in malaria-endemic populations on the Pacific coast of Colombia, where most of malaria cases are caused by Plasmodium vivax infections." (PMID 27225440, 2016). "A similar study should be conducted in the peak malaria season to determine the consequences asymptomatic P. falciparum carriage has on malaria transmission as well as identify association between G6PD and malaria in these same children during the peak season." (PMID 27456336, 2016). "A previous study showed that 20.8 % of the Thai and Burmese populations who reside in malaria-endemic areas (western, northern, northeastern, southern, eastern, and central regions) of Thailand are G6PD deficient." (PMID 27109515, 2016). "The frequency of deficient variants of glucose-6-phosphate dehydrogenase (G6PDd) is particularly high in areas where malaria is endemic." (PMID 26249834, 2015). "Further, population genetic analyses of the G6PD locus indicate that these mutations have arisen recently in certain geographical areas as a result of positive selection exerted by malaria." (PMID 26249834, 2015). "Further studies are needed to definitively establish the mechanisms by which G6PD deficiency confers an advantage against malaria in heterozygous individuals." (PMID 26686045, 2015). "There were some weaker X chromosome-specific associations, with protection from severe malaria phenotypes due to the G6PD A- alleles (202A/376G) in females." (PMID 25805752, 2015). "Population studies on relationships between genetic polymorphisms in the G6PD gene and phenotypic characteristics in uncomplicated malaria are rare." (PMID 25885177, 2015). "The global distribution of G6PD-deficient variants resembles the geographical distribution of malaria and this supports the thinking that G6PD deficiency confers some protection against malaria." (PMID 25885097, 2015). "It is, therefore, important to note that there is a major impact of natural selection that occur in malaria hyper-endemic areas, such as Africa, where the numbers of G6PD-deficient homozygous females in populations are very rare." (PMID 25885177, 2015).
malaria (continued). "Reports on comparisons between G6PD gene mutations and disease status of severe and complicated malaria are abundant." (PMID 25885177, 2015). "Enhanced susceptibility to eryptosis presumably confers protection against a severe course of malaria in several genetic erythrocyte disorders, such as sickle-cell trait, beta-thalassemia-trait, homozygous Hb-C and homozygous G6PD-deficiency." (PMID 26008229, 2015). "Ensuring safe use of 8-aminoquinolines depends on additional development of simple, highly sensitive G6PD deficiency diagnostic tests suitable for routine use in malaria-endemic areas." (PMID 25385861, 2015). "Very high linkage disequilibrium across this locus allowed us to distil this SNP diversity into just 4 G6PD alleles, ranging in frequency from ∼6% to >60%, and 8 common genotypes (>1%), 2 of which are associated with protection from severe malaria." (PMID 25671784, 2015). "This study was conducted to identify variants within the G6PD gene present in a population residing in a malaria-endemic area in southern Sri Lanka." (PMID 25885177, 2015). "Recent research suggests that as malaria elimination efforts intensify, identifying G6PD-deficient (G6PDd) individuals prior to treatment is essential to protect patients from potential haemolytic reactions." (PMID 26249834, 2015). "A database created during the 1992–1993 malaria epidemic for the same individuals was used to assess the associations between the G6PD SNPs and parasite density or disease severity of uncomplicated malaria infections." (PMID 25885177, 2015). "This study describes a set of G6PD mutations present in a Sri Lankan population and their association with uncomplicated malaria." (PMID 25885177, 2015). "In a particularly influential study done in The Gambia and Kenya, the authors concluded that both G6PD deficient hemizygous boys and heterozygous girls were protected from severe malaria." (PMID 26686045, 2015). "Although G6PD A- deficiency is known to protect against severe malaria in African populations, the underlying genetic mechanisms are not well understood." (PMID 25671784, 2015). "X-linked Glucose-6-phosphate dehydrogenase (G6PD) A- deficiency is prevalent in sub-Saharan Africa populations, and has been associated with protection from severe malaria." (PMID 25671784, 2015). "Despite these limitations, genotyping of the 202A/376G G6PD A-allele (with ∼12% of normal enzymatic activity) has been used extensively in epidemiological studies to investigate protection against severe malaria." (PMID 25671784, 2015). "The risk of drug induced haemolysis in relatively small G6PD deficient subpopulations needs to be balanced with the risk of anaemia and other detrimental effects due to recurrent episodes of malaria in all vivax patients." (PMID 26416229, 2015). "Factors such as divergent selection forces from different malaria parasite species and geographical separation have caused significant differences in distribution of different G6PD mutations." (PMID 26226515, 2015). "In a population where the frequency of G6PD-deficient X chromosomes is 15% and the frequency of an ‘−α’ alpha thalassaemic deletion is 0·25 (both perfectly plausible in malaria-endemic regions), if g4 ≤0·4 then OTOFT sensitivity in males drops below 93%." (PMID 25521998, 2015). "Here we have identified 68 G6PD polymorphisms and analysed 29 of these (i.e. those with a minor allele frequency greater than 1%) in 983 severe malaria cases and controls in Tanzania." (PMID 25671784, 2015). "For instance, the temporary induction of G6PD- (glucose-6-phosphate dehydrogenase) deficiency was proposed to mimic the natural immunity of individuals with this gene mutation against malaria." (PMID 24983392, 2014). "For example, the enzyme G6PD is involved in malaria protection but its homozygous state predisposes to hemolytic anemia." (PMID 24847360, 2014).
malaria (continued). "While G6PD-deficient males who were malaria smear positive were 94.4% (17/18), females of the same category were 87.6% (13/15)." (PMID 25406667, 2014). "G6PD A- deficiency is known to associate with reduced risk of severe malaria, and the 202A polymorphism has been used as a genotypable surrogate." (PMID 25015414, 2014). "Here G6PD polymorphisms are characterized in Dogon and Fulani ethnic groups in rural Mali (n = 712), where malaria is meso-endemic and transmission rates inside and outside of villages are identical." (PMID 25015414, 2014). "Since the global distribution of G6PD-deficient variants resembles the geographical distribution of malaria, it has been postulated that G6PD deficiency confers some protection against malaria." (PMID 24853873, 2014). "Methylene blue has also been investigated clinically for malaria, although it is slow acting and there are potential haemolytic effects of this compound in glucose-6-phosphate dehydrogenase-deficient individuals." (PMID 24731288, 2014). "From the perspective of protecting individuals from clinical malaria, HbAS genotype has showed a clear advantage and superiority as compared with HbAC and G6PD deficient genotypes in our study population." (PMID 25470251, 2014). "Selection pressure on G6PD is thought to be due to protection from malaria which is a major cause of death in childhood in Africa." (PMID 24690327, 2014). "Thirty (90.9%) out of the 33 G6PD-deficient participants were malaria smear positive which was significantly higher than the incidence of malaria among normal individuals for the enzyme (p < 0.0001)." (PMID 25406667, 2014). "Evidence of association of these G6PD polymorphisms and mild malaria was assessed in both ethnic groups using genotypic and haplotypic statistical tests." (PMID 25015414, 2014). "The magnitude of the REHH for CYP2C19*2 in Yoruba is similar to that observed for G6PD-202A (glucose-6-phosphate dehydrogenase deficiency) which is thought to confer a 50% reduction in risk of malaria." (PMID 24690327, 2014). "This is in keeping with longitudinal studies on the relationship between malaria and G6PD polymorphisms that have shown that G6PD A- individuals have lower incidence of severe malaria." (PMID 24943486, 2014). "Approximately 160 genetic variants causing clinical deficiency of G6PD have been characterized, and the geographical distribution of these alleles is closely related to populations’ history of exposure to endemic malaria." (PMID 25015414, 2014). "Despite its prevalence and hindrance to malaria control, the spatial patterns of the genetically and clinically diverse G6PD mutations are poorly documented globally; this knowledge gap, highlighted by others, constitutes the focus of the present study." (PMID 24228846, 2013). "The selective advantage of G6PD deficiency under malaria pressure has left its mark in the human genome as a “selective sweep” surrounding the G6PD gene." (PMID 23537118, 2013). "There is a need for a G6PD deficiency test that can be used in the same context of malaria rapid diagnostic tests." (PMID 23961874, 2013). "This study confirms previously known genetic associations with protection from severe malaria (HbS, G6PD)." (PMID 23144702, 2012). "The lack of difference in the occurrence of haemoglobinuria between G6PD-normal and deficient children suggests that G6PD deficiency is not a significant independent determinant in patients with severe malaria." (PMID 23039275, 2012). "G6PDd is of pertinence to malaria treatment due to the potentially dangerous consequences of exposing G6PD deficient individuals to the vitally important anti-malarial drug primaquine." (PMID 23152723, 2012). "The contribution of genetics in susceptibility to malaria has been well documented, with the sickle cell trait, haemoglobin C variants and glucose-6-phosphate dehydrogenase deficiency conferring protection against severe malaria." (PMID 22594374, 2012).
malaria (continued). "The incidence of haemoglobinuria, its association with clinical features of malaria and the G6PD status was documented among children with severe malaria attending the tertiary care facility at the University College Hospital, Ibadan." (PMID 23039275, 2012). "As a benefit, however, G6PD deficiency provides resistance to malaria and therefore even strongly deleterious alleles rise to considerable frequencies in populations where malaria infections are epidemic." (PMID 23071458, 2012). "This study confirms previously known genetic associations with protection from severe malaria (HbS, G6PD and α+- thalassaemia)." (PMID 23144702, 2012). "For example, P. falciparum is found across Africa and Asia, as are the variants of haemoglobin and G6PD that provide malaria resistance." (PMID 23088866, 2012). "Prospective studies further investigating the Duffy and G6PD status and its relation to species-specific malaria risk are, therefore, urgently needed." (PMID 23217064, 2012). "Larger sample size from different malaria endemic is required to obtain accurate genetic mapping of G6PD variants in Burmese and Thai population residing in malaria endemic areas of Thailand." (PMID 22171972, 2011). "It is postulated that the high frequency of G6PD deficiency has arisen because G6PD deficient variants confer some protection or resistance against malaria caused by Plasmodium falciparum and Plasmodium vivax." (PMID 22171972, 2011). "The CDA clinical trial programme was terminated because of an increased risk of drug-related haemolysis with CDA in G6PD-deficient compared with G6PD-normal malaria patients." (PMID 21849081, 2011). "Some of those diseases have similarly been shown to favourably influence the course of malaria, i.e. sickle-cell trait, beta-thalassaemia-trait, homozygous Hb-C and G6PD-deficiency as well as iron deficiency." (PMID 21599958, 2011). "A number of different G6PD deficient variants have reached polymorphic frequencies and each has a characteristic distribution in parts of the world where malaria is currently or was previously endemic." (PMID 22171972, 2011). "Worldwide, an estimated 400 million people are G6PD deficient with the distribution corresponding to areas in which malaria is, or has been, prevalent." (PMID 21849081, 2011). "Results indicate difference in the prevalence and distribution of G6PD gene variants among the Thai and Burmese populations in different malaria endemic areas." (PMID 22171972, 2011). "Recent reports also suggest that the malaria parasite can adapt itself to grow in these variant erythrocytes by producing its own G6PD." (PMID 22171972, 2011). "According to this observation, prevalence of G6PD deficient variants appeared to be high and variable in the western region of Thailand where malaria incidence is the highest of the country." (PMID 22171972, 2011). "The geographical distribution of malaria is remarkably similar to the world distribution of deficient G6PD variants." (PMID 22171972, 2011). "This trial was conducted in 2004 to evaluate the safety and effectiveness of CD and comparison with artemether-lumefantrine (AL) under conditions of routine use in G6PD normal and G6PD deficient patients with uncomplicated malaria in The Gambia." (PMID 21666744, 2011). "The present trial was conducted in 2004 to evaluate the safety of CD and its effectiveness in operational settings in comparison with AL, and to compare effects of these drugs on anaemia in G6PD normal and G6PD deficient patients with uncomplicated malaria." (PMID 21666744, 2011). "Glucose-6-phosphate dehydrogenase (G6PD) deficiency is common in populations living in malaria endemic areas." (PMID 21849081, 2011). "The strong protection against severe malaria conferred by the HbS, G6PD and the alpha-thalassemia mutations illustrate the striking selection pressure of malaria on the human genome." (PMID 20585394, 2010).
malaria (continued). "Dapsone is known to induce hemolysis in G6PD-deficient individuals, who represent as much as 15% of the sub-Saharan Africa population, where over 90% of global malaria cases and deaths occur [Olliaro and Wells, 2009]." (PMID 21399701, 2010). "G6PD variants correlates with historical distribution of malaria and the mutant allele (A-) encoding G6PD with 10%-50% of abnormal enzyme activity is widespread in Africa." (PMID 21092137, 2010). "They found a 52% reduced risk of uncomplicated malaria in G6PD-deficient females when the deficiency was assessed using enzyme activity." (PMID 20927393, 2010). "Deficiency in G6PD, a pivotal enzyme in the pentose phosphate metabolic pathway that protects against oxidative stress, simultaneously increases the resistance to malaria." (PMID 20008396, 2010). "With genetic results now available, we assessed the difference in risk of malaria between G6PD deficient individuals, as defined by enzymatic assay or genotype." (PMID 19789650, 2009). "Along those lines clearance of ring stage Plasmodium-infected erythrocytes is accelerated by sickle-cell trait, beta-thalassaemia-trait, homozygous Hb-C and G6PD-deficiency, genetic conditions associated with a relatively mild course of malaria." (PMID 19442289, 2009). "Data presented here show that malaria-infected GR-deficient RBCs behave very similarly to infected G6PD-deficient RBCs." (PMID 19806191, 2009). "Study objectives were to compare CDA and AL efficacy in uncomplicated P. falciparum malaria and further define the CDA safety profile, in particular, its hematological safety in G6PD-deficient malaria patients." (PMID 19690618, 2009). "There is a paucity of information regarding glucose-6-phosphate dehydrogenase (G6PD) deficiency in endemic areas for malaria in Latin America." (PMID 19370159, 2009). "We directly compared those changes to GR-sufficient control cells as well as to analogous data obtained with malaria-infected G6PD-deficient RBCs and to senescent RBCs." (PMID 19806191, 2009). "We found that G6PD-deficient females, but not males, were significantly protected against uncomplicated malaria, but this protection was only seen when G6PD deficiency was described using enzyme activity." (PMID 19789650, 2009). "Effect of G6PD activity cut-off criteria on the association analysis of G6PD status and malaria incidence." (PMID 19789650, 2009). "We found that G6PD-deficient females were significantly protected against uncomplicated malaria, but this protection was only seen when G6PD deficiency is described using enzyme activity." (PMID 19789650, 2009). "Clinical association studies have yielded varied results regarding the impact of glucose-6-phosphate dehydrogenase (G6PD) deficiency upon susceptibility to malaria." (PMID 19789650, 2009). "It is possibly this change in treatment for malaria from quinine to the artemisinin derivatives that has lead to significantly less drug induced haemolysis in Vietnamese individuals that are G6PD-deficient and infected with malaria." (PMID 19589177, 2009). "58.5% of the patients with haemoglobinuria were G6PD deficient, 25.6% had malaria confirmed by a positive blood smear and 17% received anti-malarial treatment (either quinine or primaquine)." (PMID 19589177, 2009). "Based on the composite endpoint data, CDA has an unacceptable risk:benefit profile versus AL for the treatment of malaria in G6PD-deficient patients." (PMID 19690618, 2009). "The most common G6PD deficiency in sub-Saharan Africa is G6PD A-, which is believed to have been selected by the malaria parasite." (PMID 18215251, 2008). "Pro-oxidant drugs, including antimalarial drugs associated with haemolysis in G6PD-deficient individuals are used commonly in malaria endemic areas." (PMID 19112496, 2008). "Deficiency in the X-linked glucose-6-phosphate dehydrogenase (G6PD) gene reduces the risk of developing severe malaria." (PMID 18215251, 2008).